PPARG (peroxisome proliferator activated receptor gamma)
Diseases named in the same sentence as PPARG in open-access papers (continued):
Sharing a sentence is not in itself a finding about the gene and the disease.
Obesity (continued). "As is known to all, PPARG could promote adipocyte differentiation and adipogenesis; moreover, obesity is a risk factor for asthma." (PMID 36105239, 2022). "Meta-analysis between the rs3856806 polymorphism in PPARG and obesity indexes." (PMID 35846293, 2022). "Furthermore, a higher prevalence of metabolic syndrome has been found in individuals with genetic mutations combining PPARg and fat mass and obesity-associated FTO." (PMID 36297109, 2022). "For instance, C/EBPα could induce PPARγ expression by identifying the C/EBP effector domain of the PPARγ promoter, and C/EBPα may act as a positive regulator binding to fat mass and obesity associated gene (FTO) promoter and activates the gene transcription." (PMID 33502338, 2021). "Indeed, its results increased in fatty liver disease associated with obesity in both animal and human models and the inhibition/knockdown of PPARγ ameliorates fatty liver in obese and NAFLD conditions." (PMID 34679777, 2021). "The PPARγ gene encodes peroxisome proliferator-activated receptor gamma, an enzyme that participates in adipogenesis and lipogenesis in mammals and birds and plays important roles in the development of obesity." (PMID 32810939, 2021). "In addition, previous study showed that through activating the p38MAPK and p44/42 signaling pathways, probiotic supplement inhibited PPARγ, and alleviated the obesity development and its associated metabolic disorders." (PMID 34926547, 2021). "In another case-control study (obese subjects vs. lean controls), the relationship between a genetic variant (the Pro12Ala polymorphism) of the peroxisome proliferator-activated receptor gamma gene (PPAR gamma) and the risk of obesity depending on dietary intake was explored." (PMID 34684345, 2021). "A study performed confirmed the association between PPARG and obesity." (PMID 33505493, 2021). "Therefore, investigations of the association between CD24 and obesity and weight gain in humans should consider gender-dependent associations of PPARγ." (PMID 33467499, 2021). "Phosphorylation at S273 of Pparγ is positively associated with obesity in rodents." (PMID 33804020, 2021). "FTO: fat mass and obesity-associated; PPARγ: peroxisome proliferator-activated receptor-gamma." (PMID 33729310, 2021). "However, dissecting the relative contribution of these two cell types in governing pioglitazone-prevented aortic stiffening caused by obesity would further require a macrophage or fibroblast-specific PPARγ knockout." (PMID 33781257, 2021). "Obesity is the most important risk factor for OSA and PPARG is related to obesity." (PMID 31044373, 2020). "Moreover, alpha-mangostin treated diet induced obesity mice experienced weight loss, improved glucose and lipid profile and reduced liver fat accumulation through a Peroxisome proliferator-activated receptor gamma and SIRT-1-AMPK pathway." (PMID 32962190, 2020). "Additionally, PPARG had been implicated in the pathology of numerous diseases including obesity, diabetes, atherosclerosis and cancer." (PMID 33083004, 2020). "FFA treatment can cause up-regulation of PPARγ via PGC1α in liver cells, and both PGC1α and PPARγ were elevated in the liver of mice with nonalcoholic fatty liver disease, a disease closely associated with obesity and HFD consumption." (PMID 33076522, 2020). "PPARG has been linked to development of obesity and may play an important role in the pathophysiological mechanisms underlying OSA." (PMID 31044373, 2020). "Moreover, It was known that Cdk5-mediated phosphorylation of PPARγ at Ser-273 was obesity-linked phosphorylation site." (PMID 32190280, 2020). "It has been found that the activation of PPARα and PPARγ attenuates total free fatty acid and triglyceride accumulation, which may reduce the risk of obesity, diabetes, and atherosclerosis." (PMID 31010169, 2019).
Obesity (continued). "Specifically, the interaction of COUP-TFII with PPARγ and β-catenin could have a potential impact in the regulation of oxidative stress, inflammation and obesity development, which are linked to or are causative agents of diabetes." (PMID 31906104, 2019). "PPARG down-regulation leads to impaired capacity of adipose tissue to accumulate lipids, which in turn provokes ectopic lipid accumulation, insulin resistance and other obesity-associated comorbidities." (PMID 30642114, 2019). "Interestingly, a previous study has shown an increase in PPARG methylation and a decrease of PPARG mRNA associated with this DNA methylation increase in db/db and diet-induced obesity mice, which is in line with our results." (PMID 30642114, 2019). "The disruption of PPARγ specifically in myeloid cells also predisposes mice to the development of diet-induced obesity, insulin resistance, and glucose intolerance, whereas activation of PPARγ within macrophages promotes lipid efflux, thereby stabilizing atherosclerotic lesions." (PMID 30857223, 2019). "However, a meta-analysis concluded that PPARG variants contributed to human adiposity variation and predisposition for obesity." (PMID 29679223, 2018). "PPARγ is the most extensively studied member of the PPARs family; it is well known for its role in peripheral metabolism, and has been implicated in the pathology of numerous diseases including diabetes, stroke, cancer, and obesity." (PMID 29723294, 2018). "PPARγ is a critical transcriptional regulator of adipogenesis in mammals, is closely related to regulation of lipids and glucose metabolism, and is associated with the control of obesity and related diseases." (PMID 30034368, 2018). "The obesity suppression was associated with reductions in expression of adipogenic proteins, such as C/EBPα and PPARγ, increases in expression of lipolytic enzymes, such as adipose triglyceride lipase (ATGL) and hormone-sensitive lipase (HSL), in WAT of HFD-fed mice." (PMID 30463291, 2018). "Hence our decision to analyze relationships between particular components of MetS and selected gene polymorphisms, namely peroxisome proliferator-activated receptor gamma (PPAR-γ), fat mass and obesity-associated (FTO), and melanocortin-4 receptor (MC4R)." (PMID 29315078, 2018). "In addition, a study performed on mothers and their newborns emphasized that homozygous CC carriers of the PPARG genotype presented a higher risk for obesity than heterozygous newborns." (PMID 30338250, 2018). "The aim of the present study was to assess the independent contributions of LEPR (rs1137101), FTO (rs9939609), MC4R (rs2229616 and rs17782313), and PPARG-2 (rs1801282) polymorphisms for clinically overweight or obesity phenotypes and endocrine-metabolic traits in prepubertal children." (PMID 29679223, 2018). "In addition, PPARγ is suggested to regulate the inflammatory potential of adipose tissue macrophages, a central player in obesity-associated systemic insulin resistance." (PMID 30111834, 2018). "A recent study confirmed the association between PPARG and obesity in young adults." (PMID 30338250, 2018). "However, till now, no study focused on impact of gene-environment interaction between PPARG and obesity on T2DM risk in Chinese population." (PMID 28123453, 2017). "However, till now, no study focused on the impact of gene- environment interaction between PPARG and obesity on T2DM risk in Chinese population." (PMID 28123453, 2017). "The results indicated that appropriate functional antagonism of PPARγ may be a logical approach for protection against obesity and obesity-associated diseases." (PMID 28464894, 2017). "Despite the potential importance of SIRT1 in adipogenesis and obesity, the epigenetic mechanism underlying PPARγ repression is largely unknown." (PMID 29233982, 2017). "Finally, PPARG has been implicated in the pathology of numerous diseases including obesity and diabetes." (PMID 29190701, 2017).
Obesity (continued). "Interestingly, the decreased gene expression of Pparγ has been linked to inflammatory processes associated with obesity and insulin resistance, an issue that enhances the importance of the inflammatory responses in the developmental programming." (PMID 28082878, 2016). "Many mutations in the PPARγ gene are associated with obesity and diabetes-related phenotypes." (PMID 28042289, 2016). "In respect to the association of genotypes with obesity, under an additive model, the ORwas 1.25 (CI = 0.73 – 2.15) for PPARG rs1801282, 1.27 (CI = 0.82 –1.98) for FTO rs9939609, 1.47 (CI = 0.78 – 2.74) forADIPOQ rs4632532 and 1.43 (CI = 0.76 – 2.74) forADIPOQ rs182052." (PMID 27560839, 2016). "In conclusion, this study analyzed environment and genetic aspects of obesity and foundsignificant associations between PPARG rs1801282 and triglycerideslevels, ADIPOQ rs4632532 and HDL levels, and FTOrs9939609 with cholesterol, LDL and anthropometric measurements." (PMID 27560839, 2016). "Consequently, the severity of obesity correlated with the low proportion of adipose Tregs and their PPARγ expression in vivo, and was linked with the diminished ability of ATMs to induce Tregs with PPARγ expression in vitro." (PMID 26582486, 2015). "Obesity is the top ranking disease associated to PPARG (0.812)." (PMID 25877637, 2015). "Phosphorylation of PPARγ at Ser273 by cyclin-dependent kinase 5 (Cdk5) was recently linked to obesity, and anti-diabetic PPARγ ligands (e.g. the thiazolidinedione rosiglitazone) were shown to inhibit the Cdk5-mediated phosphorylation of PPARγ in adipose tissue." (PMID 25083916, 2014). "However, to our knowledge, this is the first study to investigate the associations between the gene expression of important obesity markers (adipokines and PPARγ) in AT and POP concentrations in fat from obese patients." (PMID 24427296, 2014). "Our data confirmed the role of FTO, CTNNBL1, LEPR and PPARG in obesity predisposition." (PMID 24879436, 2014). "Due to PPARγ’s role in controlling lipid/glucose metabolism, it is regarded as a physiological factor associated with predispositions to hyperlipidemia, insulin resistance, type 2 diabetes mellitus, obesity and cardiovascular diseases." (PMID 23799144, 2013). "As a result, it has been suggested that PPARγ deficiency might prevent or attenuate the insulin resistance associated with obesity and other factors." (PMID 24330836, 2013). "Dysregulated metabolism is implicated in obesity and other disease conditions like type 2 diabetes mellitus and cardiovascular diseases, which are linked to abnormalities of peroxisome proliferator-activated receptor gamma (PPARγ)." (PMID 23389305, 2013). "So, it appears all of studied adipokines might have association with PPARγ level and might simultaneously be involve in some common pathway to make susceptible obese subjects for MetS and other obesity related condition." (PMID 24330836, 2013). "In addition to their capacity to enhance the transcriptional activity of PPARγ, PPARγ agonists have a separable biochemical activity, blocking the obesity-linked phosphorylation of PPARγ at Ser-273 by Cdk5." (PMID 24454336, 2013). "Although, PPARγ genotypes considered as modulator factor in MetS risk in previous studies, but there was not any reports regarding to association between circulating PPARγ and susceptibility to MetS in obesity." (PMID 24330836, 2013). "We also found that p-F11 inhibits obesity-linked phosphorylation of PPARγ at Ser-273 by Cdk5." (PMID 24454336, 2013). "In the current studies, our aim was to identify whether there is an interplay between FFAs and PPARγ in the context of obesity-associated inflammation." (PMID 22529965, 2012). "Paradoxically, partial loss of PPARγ in heterozygous knockout mice also leads to increased insulin sensitivity and resistance to high fat diet-induced obesity because lower levels of PPAR γ result in decreases in overall body weight gains and fat contents 5,6,7." (PMID 22859932, 2012).
Obesity (continued). "Recent studies of neuronal PPARγ have highlighted its critical role in the regulation of energy balance and suggest that the inhibition of central PPARγ expression protects against the hyperphagia and reduced energy expenditure, and thus weight gain, associated with high fat diet induced obesity." (PMID 23049863, 2012). "Indeed, activation of PPARγ by the thiazolidinediones (TZDs) pioglitazone or rosiglitazone improves insulin resistance associated with obesity and diabetes." (PMID 22991504, 2012). "Together, these studies suggest that induction of PPARγ by alterations in miR-27a/b and/or miR-130 expressions might be linked to the development of obesity in rodents and humans." (PMID 23024649, 2012). "Among them, PPARγ is expressed predominantly in adipose tissue and macrophages, is closely related to the regulation of lipid and glucose metabolisms, and is associated with the control of obesity and related diseases." (PMID 23319937, 2012). "In humans, an activating mutation in PPARγ leads to increased adipogenesis and obesity." (PMID 20182546, 2010). "Differentiating preadipocytes with low C/EBPα and PPARγ can still accumulate lipid when exposed to fatty acids but are insulin resistant and dysfunctional, consistent with accretion of the large, insulin-resistant, C/EBPα- and PPARγ-deficient fat cells in obesity that are associated with diabetes." (PMID 20701600, 2010). "Similarly to PPARα deficiency, PPARγ deficiency in adiposetissue (PPARγ-adiposeKO) was reported to protect from obesity andinsulin resistance caused by HFD." (PMID 17389764, 2007). "Additionally, they can elevate the risk of obesity in children and adolescents by activating PPARγ (peroxisome proliferator-activated receptor gamma) and PPARα (peroxisome proliferator-activated receptor alpha), pivotal factors in lipid and glycogen metabolism." (PMID 40066031, 2025). "For instance, the identification of FTO or PPARG risk alleles could guide early lifestyle interventions in individuals at high risk for obesity or type 2 diabetes, while variants in COL1A1 or IL6 may allow the identification of increased susceptibility to tendon or ligament injuries." (PMID 41300761, 2025). "Obesity has been reported as a potential risk factor for placenta accreta, and we hypothesize that this could be attributed to the close relationship between lipid metabolism and PPARG expression and function." (PMID 40705926, 2025). "Our findings underscore the potential of emodin as a naturally sourced combination partner for PPARγ agonists, offering a clinically actionable strategy to overcome weight gain-associated discontinuation in the pharmacotherapy of type 2 diabetes with obesity comorbidity." (PMID 41471299, 2025). "Thus, PPARγ is a novel target of Par-4 that may play a role in adipogenesis associated with obesity regulation by Par-4." (PMID 39273065, 2024). "Therefore, dietary tannic acid may also regulate the metabolic disorders caused by a high-fat diet through the AMPK and PPARγ signaling pathways, thereby inhibiting the formation of obesity." (PMID 36359937, 2022). "Recently, researchers have demonstrated that the serine 273 site of PPARγ is linked to obesity and insulin resistance, and other studies have shown that the phosphorylation of S273 can inversely reduce the total protein level of PPARγ in white adipose tissue through a yet unknown mechanism." (PMID 35061665, 2022). "Moreover, strong correlative evidence obtained on human tissues supports the hypothesis that PPARγ is activated in obesity and is closely associated with ACBP expression in metabolically relevant tissues." (PMID 35436993, 2022). "Altogether, the existing data demonstrate that PFOS and/or PFOA exposure may promote adipogenesis through the up-regulation of PPARγ and C/EBPα signaling, thus contributing to an increased risk of obesity, although the epidemiological data have yet to confirm this association." (PMID 35202251, 2022).
Obesity (continued). "Therefore, this study may also suggest that the Pro12Ala variant of the PPARγ gene probably had a gender-specific effect and was related to susceptibility to obesity in this population." (PMID 36551995, 2022). "Our findings ultimately support a model in which ANGPTL8 upregulated the expression of PPARγ and c/EBPα by inhibiting the Wnt/β-catenin signaling pathway and promoting the adipogenic differentiation of MSCs, resulting in lipid deposition in multiple organs and causing obesity in male mice." (PMID 36034432, 2022). "Furthermore, the combination of GTPs with PPARγ agonist may be an optimal therapy for the diabetic patient associated with obesity and osteoporosis." (PMID 36547073, 2022). "Authors showed also a correlation between miR-130 downregulation and the increase of PPARγ mRNA levels, a major regulator of adipogenesis, suggesting that this miRNA reduced adipogenesis through the repression of PPARγ and that this deregulation was linked to human obesity." (PMID 34299336, 2021). "Whether the obesity caused by Crtc1 deletion links to Pparγ remains unexplored." (PMID 33912553, 2021). "Moreover, previous evidence has suggested that PPARG may be a risk factor for cardiovascular diseases such as metabolic syndrome, obesity, diabetes and hypertension." (PMID 34239024, 2021). "Since the expression of the MR is directly regulated by PPARγ, and free fatty acid-activated PPARγ signaling is upregulated in lipid-associated macrophages during obesity, this transcription factor could be one of the key players in the regulation of MR expression and shedding." (PMID 34721436, 2021). "Thus, improvement of the PVAT microenvironment by PPARγ agonists may provide a novel therapeutic strategy against arterial stiffening associated with obesity." (PMID 33781257, 2021). "In turn, the role of toxic metal exposure in obesity may be associated with similar mechanisms, as well as the direct impact of metal toxicity on adipogenesis through modulation of key transcription factors including PPARγ and C/EBPα." (PMID 34360489, 2021). "Among these, the nuclear receptor PPARγ and C/EBPα are master regulators of adipogenesis, playing a crucial role in the differentiation and function of mature adipocytes The activation of these nuclear receptors in adipocytes has been reported to enhance insulin resistance associated with obesity." (PMID 32260306, 2020). "Indeed, loss of PPARγ expression in the liver exacerbates dysmetabolism associated with obesity." (PMID 31903139, 2020). "It has been reported that miR-27b is down-regulated in in vitro cultured adipocytes and adipose tissue in obesity-related models and that miR-27b impairs adipocyte differentiation in 3T3-L1 cells and human adipose-derived mesenchymal stem cells via its associations with PPARγ and C/EBPα." (PMID 31930115, 2019). "Additionally, PPARG has been implicated in obesity, diabetes, and atherosclerosis." (PMID 30934777, 2019). "The altered expression of PPARγ and C/EBPα, etc. could induce adipocyte differentiation, and the inhibition of adipocyte differentiation has been proved that was associated with prevention and treatment of obesity." (PMID 30177649, 2018). "The transcriptional signature of VAT Treg cells from obese mice showed a strong correlation with the transcriptional changes induced by deficiency of PPARγ, suggesting that obesity might exert its impact on VAT Treg cell through either direct or indirect modulation of PPARγ." (PMID 30323806, 2018). "Owing to the importance of PPARγ in lipogenesis and lipid metabolism in humans and other animals, the epigenetic mechanisms underlying transcriptional regulation of PPARγ will remain a research focus in the field of lipid biology and medicine and may result in improved treatments for obesity." (PMID 30034368, 2018).